INS (insulin)
Diseases named in the same sentence as INS in open-access papers (continued):
Sharing a sentence is not in itself a finding about the gene and the disease.
helminth infection (23 papers, 2012 to 2025). "Altogether, these results may challenge the current paradigm, where promoting AAMs is associated with enhanced tissue insulin sensitivity, as previously reported in response to helminth infection or helminth-derived molecules." (PMID 35720355, 2022). "Previous studies showed that some helminths infection or its derived antigens reduce blood glucose and improve insulin sensitivity." (PMID 33413119, 2021). "The observation regarding decreasing levels of IGF-1 with an increasing number of helminth infections in this study might suggest more disruption of nutrient intake, which in turn could directly or indirectly be linked to changes in the BMI and fasting insulin level." (PMID 33149205, 2020). "Endemic helminth infections are thought and in part shown to affect insulin sensitivity and resistance through immune-modulating properties and by reducing energy intake and altering energy balance." (PMID 30396368, 2018). "Importantly, the transition away from helminth infection has been identified as a potential contributor to metabolic diseases since they consume glucose and lipids, heighten insulin sensitivity, and increase immune activation." (PMID 39033292, 2024). "Furthermore, these changes correlate with improved insulin signaling and sensitivity, suggesting that modulation of the microbiota by helminth infection has a positive effect on the glucose homeostasis of hosts." (PMID 35281054, 2022). "Another mechanism by which helminth infection could affect serum free IGF-1 levels might be mediated by insulin." (PMID 33149205, 2020). "A lower level of insulin in helminth infection could lead to an increase in IGFBP-1 and -2 levels which eventually will result in a lower level of free IGF-131,32." (PMID 33149205, 2020). "Increasing experimental evidence has revealed that helminth infection may help the host to improve insulin sensitivity and metabolic function against T2DM development by triggering innate and acquired immunoregulatory responses as well as by altering the gut microbiota." (PMID 35639713, 2022). "These helminths infections may increase circulating levels of interleukin (IL)-4, IL-5, IL-10 and IL-13 which may act to blunt or reverse the Th1-induced inflammation in metabolic tissues resulting in increased insulin sensitivity." (PMID 35077485, 2022). "Hence, Th2 immune skewing such as during chronic helminth infections improves insulin sensitivity." (PMID 34769439, 2021). "Interestingly, helminth infection and treatment with helminth-derived molecules have also been shown to improve insulin sensitivity and glucose homeostasis in various rodent models of T2D, at least partly through induction of a type 2 immune response in metabolic organs." (PMID 32614822, 2020). "Helminth infection can alter Th1/Th2 immune polarization, reduce systemic levels of Th1/Th17 pro-inflammatory cytokines (IL-4 over IL-17, TNF-α and IFN-γ), switch macrophages from M1 to M2 pattern, or change intestinal microbial diversity, all of which lead to increased insulin sensitivity." (PMID 35639713, 2022). "Chronic helminth infection is known to trigger a potent TH2 immune response together with T-cell hyporesponsiveness through induction of a regulatory network, which have been both suggested to dampen meta-inflammation and restore tissue-specific and whole-body insulin sensitivity." (PMID 32614822, 2020). "Furthermore, no data on the history and intensity of helminth infections nor history of deworming are present, which prevents strong conclusions on the relationship between STH infections, the immune system and insulin sensitivity." (PMID 26061042, 2015).
hepatitis B (23 papers, 2016 to 2025). "Major newly found risk factors were autoimmune liver disease, BRCA gene mutation, co-infection with hepatitis B and C, and insulin use." (PMID 40584837, 2025). "Previous studies have suggested that hepatitis B patients are more susceptible to PHLF, as HBV-expressing hepatocytes exhibit reduced sensitivity to insulin, impairing liver regeneration." (PMID 40530012, 2025). "Among the top 10 enriched KEGG pathways in both tissues are the MAPK signaling pathway, the Insulin signaling pathway, Pathways in cancer, the Hepatitis B signaling pathway, and the PI3k-Akt signaling pathway." (PMID 39552722, 2024). "Among these, 5 were relevant to immune function and other pathways, including human cytomegalovirus infection, insulin resistance, vascular smooth muscle contraction, hepatitis B, and chemokine signaling." (PMID 35172000, 2022). "Pathways with a statistical significance of p < 0.01 included the RIG-I-like receptor, cGMP-PKG, insulin resistance, tight junction, hepatitis B, and Epstein-Barr virus infection signaling pathways." (PMID 31582977, 2019). "KEGG analysis results showed that most targets in pituitary tissues were mainly involved in focal adhesion, endocytosis, insulin signaling pathway, hepatitis B and FoxO signaling pathway." (PMID 28335741, 2017). "The results identified six significantly dysregulated pathways that were involved in atropine-treated corneal epithelial cells, including glucagon signaling pathway, estrogen signaling pathway, Ras signaling pathway, insulin signaling pathway, arachidonic acid metabolism, and hepatitis B." (PMID 31540331, 2019).
Onset (23 papers, 2010 to 2026). The age group in which disease manifestations appear. "Early-onset DM is insulin-dependent and non-autoimmune, with a low prevalence of complications." (PMID 29483894, 2018).
osteosarcoma (23 papers, 2010 to 2024). A usually aggressive malignant bone-forming mesenchymal neoplasm, predominantly affecting adolescents and young adults. "Gene expression microarray analysis in a previous study identified INS as one of the core genes in osteosarcoma with pulmonary metastasis." (PMID 37285835, 2023). "In these conditions, LIMK1 phosphorylation is reduced, indicating a possible role for LIMK1 in regulating the osteosarcoma cell proliferation via the insulin/PI3K/LIMK1 signalling pathway." (PMID 36899941, 2023). "Insulin promotes the proliferation of MG63 osteosarcoma cells in a time- and dose-dependent manner, and also induces LIMK1 and cofilin phosphorylation." (PMID 36899941, 2023). "Another potential concern with use of glargine has been the findings from in vitro studies that show its ability to stimulate DNA synthesis in human osteosarcoma cell lines, much more than human insulin." (PMID 36271431, 2022). "the results of this study suggest that HAEVa has antiproliferative properties on MG-63 osteosarcoma in vitro and also inhibits in vivo the postprandial blood glucose level in dexamethasone-induced insulin-resistant rats." (PMID 36845227, 2022). "It has been demonstrated by many studies that Pi-mediated ROS production occurs in different cell types: rat osteosarcoma (MR-106 cells), insulin-secreting cells (INS-IE), human endothelial cells (EAhy926) and BAECs." (PMID 34576256, 2021). "Chronic exposure of osteosarcoma cells to IGF2 or insulin in combination with serum deprivation, successfully established an in vitro dormancy and drug-resistance model in osteosarcoma." (PMID 33816262, 2021). "Insulin analogs such as arg-insulin exhibit high pro-proliferative activity in human osteosarcoma cells with a potency at least 8 times greater than human insulin." (PMID 28424632, 2017). "It is well known that the insulin/insulin-like growth factor (IGF) pathway plays an important role in osteosarcoma tumor growth." (PMID 24216982, 2013). "Osteosarcoma tumors and cell lines express components of the pathway (including insulin, IGF-I and -II, as well as pathway receptors) that are capable of autocrine signaling." (PMID 24216982, 2013). "The IHC results illustrated that the expression of AVADVL, ATF4, INS and MAPK10 was higher in osteosarcoma tissues compared to normal tissues." (PMID 37285835, 2023). "In the present study, we analyzed the high-throughput RNA-sequencing data and clinical information of 86 osteosarcoma patients, and identified eight prognosis-related genes, including MAP3K5, G6PD, HMOX1, ATF4, ACADVL, MAPK1, MAPK10, and INS." (PMID 37285835, 2023). "In this study, we found significant differences between the prognosis of patients with low and high expression levels of ACADVL, ATF4, HMOX1, INS, and MAPK10, indicating that these genes are potential therapeutic targets of osteosarcoma." (PMID 37285835, 2023). "In U-2 OS (human osteosarcoma) cells, apigenin could trigger rapid intracellular translocation of FOXO1 which was reversed by insulin." (PMID 38629096, 2024). "It was reported that insulin induced EMT of mammary epithelial cells, while blocking insulin-like growth factor (IGF)/insulin-like growth factor-1 factor (IGF1R) signaling axis suppressed EMT of osteosarcoma cells." (PMID 37386367, 2023). "IGFBP5 primarily binds to insulin growth factors to inhibit the IGF1 and IGF2 signalling pathways, thereby inhibiting the proliferation, migration and invasion of osteosarcoma, and is a key inhibitor of in situ osteosarcoma growth and lung metastasis." (PMID 33614075, 2021). "In this perspective, we emphasize the current advances and interactions involving the insulin/IGF1R, SIRT1, and FOXOs pathways in the bone and osteosarcoma for a better understanding of the mechanisms potentially underpinning tissue degeneration and tumorigenesis." (PMID 30881341, 2019).
osteosarcoma (continued). "Osteosarcoma is a malignant bone tumour with an incidence peak coinciding with the adolescent growth spurt, a time when the hormonal milieu is characterized by high GH, IGF1 and insulin levels." (PMID 28316059, 2017). "XMetS also did not influence the effect of insulin on the proliferation of Saos-2 human osteosarcoma cells." (PMID 24533136, 2014). "To test if continuous exposure to insulin can favour tumour growth, we studied insulin/IGF1-dependent activation of ERK1/2 and Akt/PKB by Western blotting, inhibition of apoptosis by ELISA, and induction of proliferation by [3H]-thymidine incorporation in Saos-2/B10 osteosarcoma cells." (PMID 28316059, 2017). "Apigenin and luteolin were identified in our U-2 OS (human osteosarcoma) cell screening assay for micronutrients triggering rapid intracellular translocation of the forkhead box transcription factor O1 (FOXO1), an important mediator of insulin signal transduction." (PMID 25136826, 2014). "Much of the concern about insulin glargine stemmed from in vitro experiments exposing human osteosarcoma cells (Saos/B10) to insulin glargine which revealed a 6.5-fold higher affinity for the IGF-1 receptor and an 8-fold greater mitogenic action in comparison to insulin." (PMID 22685467, 2012).
ulcer (23 papers, 2010 to 2026). "In this case, we want to emphasize the potential of insulin as a supplementary treatment agent in prolidase deficiency-induced ulcer treatment." (PMID 38021973, 2023). "Ulcer-free survival was reduced in the small subset of patients with insulin-dependent patients with “excess” 2ML; however, the findings are preliminary and clearly further study in larger cohorts is needed." (PMID 38497521, 2024). "Further research is essential to elucidate the precise mechanism of action of topical insulin in healing ulcers and epithelial defects and to determine the optimal concentration of insulin in eye drops for the treatment of epithelial damage." (PMID 38276493, 2023). "Laser, insulin-liposomal gel and sucralfate are considered as possible optimal solutions for short-term relief of ulcer-induced pain." (PMID 35744034, 2022). "Diabetic patients with ulcers were randomized to receive topical insulin or placebo in a prospective, double-blind and placebo-controlled, randomized clinical trial (NCT 01295177) of wound healing." (PMID 22662132, 2012). "Topical insulin can be considered as an additional therapy for treatment-resistant ulcers." (PMID 37397672, 2023). "In addition to their well-known antioxidant effects, select polyphenols also have insulin-potentiating, anti-inflammatory, anti-carcinogenic, anti-viral, anti-ulcer, and anti-apoptotic properties." (PMID 22174658, 2011). "Furthermore, integrating systematic metabolic and inflammatory profiling, together with quantitative imaging-based ulcer measurements, would enhance understanding of insulin’s mechanism of action and help define which patient subsets may benefit most." (PMID 41303828, 2025). "↓ Blood glucose, ↓ Insulin levels, ↓ HbA1c, ↓ serum hs-CRP, ↓ plasmatic malondialdehyde (MDA) levels, ↑ plasmatic TAC, and ↓ ulcer length, improved lipidic metabolism." (PMID 40722870, 2025). "However, according to the regression analysis performed, insulin levels are important variables for the ulcer size in the RSV group, whereas CRP values are not relevant to study outcome." (PMID 24701359, 2014). "DR + AA rats, treated with OMZ, INS and PTX showed decrease in ulcer index by 39.3, 38.6 and 43.3% respectively (near to NR + AA level) while, MSE showed decrease by 63.8%, less than the value of NR + AA rats indicating better healing by MSE compared to OMZ, INS or PTX." (PMID 24192345, 2013).
cardiac arrest (22 papers, 2007 to 2025). Cessation of breathing and/or cardiac function. "On-Pump CABG, and in particular cardiac arrest-resumption, can stimulate release of inflammatory cytokines, exacerbating insulin resistance while affecting glucose metabolism in cardiac tissues, ultimately inducing a rapid increase in blood glucose." (PMID 36788548, 2023). "Glucose characteristics during 72 h after cardiac arrest according to the insulin administration method." (PMID 36584121, 2022). "Patients admitted to a tertiary care hospital for circulatory arrest and treated with both therapeutic hypothermia and protocol-based continuous insulin between January 2010 and June 2013 were included." (PMID 29075530, 2017). "Thirty-two of the 48 patients (66.7%) who were treated with TH after cardiac arrest received continuous infusion insulin therapy." (PMID 29075530, 2017). "Insulin sensitivity was identified hourly using retrospective data from 200 post-cardiac arrest patients (8,522 hours) treated with TH, shortly after admission to the intensive care unit (ICU)." (PMID 25349023, 2014). "Co-administration of dextrose with insulin has been proposed as a metabolic resuscitation strategy to enhance myocardial glucose uptake, improve cardiac contractility, and restore cellular energy balance during resuscitation from asphyxial cardiac arrest." (PMID 41597058, 2025). "Similarly, the HRs for all-cause mortality and MACEs in different models were comparable when further adjusting for ALT (Model 2), insulin (Model 3), heart rate, and prior cardiac arrest (Model 4)." (PMID 37745131, 2023). "The target temperature differed among the insulin treatment groups because the target temperature and the insulin administration method depended on the post-cardiac arrest care protocol at each hospital rather than the attending physician." (PMID 36584121, 2022). "In the IMMEDIATE trial, very early intravenous glucose-insulin-potassium for ACS patients could suppress FFAs and ultimately result in less cardiac arrest and in-hospital mortality." (PMID 31610783, 2019). "In this study, DM increased the overall risk of cardiac arrest; however, the risk for OHCA in DM patients who were treated with oral hypoglycemic agent or insulin was observed to be smaller compared to no treatment or non-pharmacotherapy only groups." (PMID 27105059, 2016). "Furthermore, although insulin is administrated subcutaneously or intravenously (bolus or continuous), the clinical difference according to the insulin administration in cardiac arrest survivors has not been investigated." (PMID 36584121, 2022). "Neither magnesium nor intensive insulin has proven beneficial after SAH or cardiac arrest." (PMID 23533956, 2013).
Hashimoto thyroiditis (22 papers, 2008 to 2026). An autoimmune disorder caused by the production of autoantibodies against thyroid tissue. "This case is particularly noteworthy because of the coexistence of Hashimoto’s thyroiditis, an autoimmune thyroid disorder known to contribute to reduced insulin sensitivity and increased cardiometabolic risk." (PMID 40656273, 2025). "Hashimoto’s thyroiditis (HT) is an autoimmune inflammation of the thyroid gland associated with alterations in glucose and insulin metabolism, therefore frequently occurring along with type 1 diabetes (T1D)." (PMID 26192189, 2015). "The improvement in insulin sensitivity, observed in both groups, was more pronounced in group B than in group A. In women with autoimmune hypothyroidism, the drug increased SPINA-GT and decreased hsCRP levels." (PMID 38051473, 2024). "In euthyroid subjects with Hashimoto thyroiditis, FABP4 concentrations were higher than in healthy controls and were directly associated with T4 and insulin concentration." (PMID 35448487, 2022). "The aim of the current real-life observational study was to compare the factors influencing the insulin and levothyroxine (LT4) requirement in patients with autoimmune polyglandular syndrome type 3 (APS-3) compared to T1DM and autoimmune hypothyroidism (AH) alone, respectively." (PMID 33099763, 2021).